ACLY (ATP citrate lyase)
Diseases named in the same sentence as ACLY in open-access papers (continued):
Sharing a sentence is not in itself a finding about the gene and the disease.
cancer (continued). "As already discussed, decreased citrate level in the cytoplasm is associated with increased expression of ACLY and FAS in cancer cells, but citrate production does not decrease due to increased glutaminolysis." (PMID 35178152, 2022). "ACLY and ACC are always upregulated to meet the demand for membrane expansion in cancer." (PMID 34986838, 2022). "Additionally, ATP citrate lyase (ACLY), the first rate-limiting enzyme in FA de novo synthesis, is upregulated in several types of cancer." (PMID 36497226, 2022). "Indeed, many of the enzymes responsible for lipid synthesis, such as ATP-citrate lyase (ACYL), acetyl-CoA carboxylase (ACC) and fatty acid synthase (FASN) are highly up-regulated in cancer." (PMID 34249759, 2021). "Of note, EMT has also been related to the emergence of cancer stem cells (CSCs), which could, therefore, be supported by the PI3K/Akt/ACLY axis." (PMID 34205414, 2021). "Bempedoic Acid (ETC-1002) as an ACLY inhibitor has been approved by the Food and Drug Administration (FDA) for decreasing LDL-C levels in atherosclerotic cardiovascular disease, and has been applied to cancer therapeutic therapy." (PMID 34075028, 2021). "Enzymes in de novo FAS pathway, including ACLY, ACC and FASN, are upregulated in numerous cancers." (PMID 34823530, 2021). "Finally, the fibronectin adhesion assay was used to assay effects of SIRT6 and ACLY on cell adhesion to the extracellular matrix (ECM), which contributes to cancer cell invasiveness." (PMID 34573442, 2021). "However, ACLY is also involved in histone acetylation and DSB repair, making this key metabolic enzyme of cancer signaling an attractive therapeutic target in combination with radiotherapy." (PMID 33202866, 2020). "Overexpression of Akt increases the expression of ACLY, ACC, and FASN in human cancer cells." (PMID 32947972, 2020). "ACLY was upregulated in COAD, COADREAD, HNSC, KIRC, and LIHC in the present study which indicates ACLY might promote tumor proliferation in these cancer types." (PMID 31828117, 2019). "Two key steps in lipid synthesis that have been thoroughly described in carcinogenesis development are catalyzed by ATP citrate lyase (ACLY) and fatty acid synthase (FASN), where their inhibition could induce apoptosis and reduce tumour growth of cancer cells." (PMID 31040908, 2019). "Both ACLY and OGDH are key metabolic enzymes that drive cancer cell proliferation." (PMID 27892457, 2016). "Also citrate can be converted to Acetyl-CoA by ATP citrate lyase (ACL) and participate in the synthesis of fatty acids and cholesterol, which are essential components of cancer cell membranes, lipid raft and lipid-modified signalling molecules." (PMID 26030804, 2015). "Inhibitors that target ACLY and ACC1 are proposed cancer therapeutics." (PMID 26452058, 2015). "This analysis resulted in the identification of several differentially regulated genes that function in normal cell metabolism including, ATP citrate lyase (ACLY) and pyruvate dehydrogenase kinase (PDK) that have previously been shown to play a role in cancer cell metabolism." (PMID 21437235, 2011). "For example, the ACLY inhibitor bempedoic acid (ETC-1002) was already authorized by the U.S. Food and Drug Administration (FDA) in 2020 as a non-statin LDL-C lowering drug for atherosclerotic cardiovascular disease, as well as being used in cancer treatment therapeutics." (PMID 38755125, 2024). "ATP-citrate lyase (ACLY), acetyl-CoA carboxylase (ACC), fatty acid synthase (FASN), stearoyl-CoA desaturase-1 (SCD1), 3-hydroxy-3-methyl-glutaryl-CoA reductase (HMGCR), and squalene epoxidase (SQLE) are overexpressed in cancer cells and are under the transcriptional control of the AR." (PMID 36674430, 2023). "SIRT2 may inhibit cancer cells from producing VEGF, CTGF, and ATP citrate lyase (ACLY)." (PMID 37175631, 2023).
cancer (continued). "Targeting ACLY, however, may not be a viable long-term treatment option, as cancer cells can upregulate acetyl-CoA synthetase (ACCS) to produce acetyl-CoA from acetate, obviating the need for citrate as a source of acetyl-CoA for FA synthesis." (PMID 35448537, 2022). "Even without ACLY activity, cancer cells can proliferate well." (PMID 39086974, 2022). "Thus, ACLY overexpression was found to be a significant negative prognostic factor for this type of cancer." (PMID 33393219, 2021). "Thus, we speculate ACLY and SLC2A1 may serve as critical linker of metabolic and histone acetylation in these cancer types." (PMID 31828117, 2019). "Inhibition of key enzymes in the DNL pathway, namely, ATP citrate lyase, acetyl-CoA carboxylase, and fatty acid synthase (FASN) can increase apoptosis without cytotoxicity to non-cancerous cells, leading to the search for and presentation of novel selective and powerful targets for cancer therapy." (PMID 29588626, 2018). "Several proteins involved in lipogenesis including ATP citrate lyase (ACL), acetyl-CoA carboxylase (ACC), fatty acid synthase (FAS), and sterol response element binding protein (SREBP) have been shown to be intimately related to cancer cell growth and survival." (PMID 25961014, 2015). "For example, silencing of ATP citrate lyase (ACLY), a cytosolic enzyme that converts citrate into a shared precursor for fatty acid and mevalonate synthesis such as acetyl-CoA, is sufficient to counteract stem cell characteristics induced in diverse cancer cell systems." (PMID 25246709, 2014). "The levels of ACLY mRNA in cancer and non-cancer tissues were determined as 104.4±100.9 and 104.9±100.6 copies/μg total RNA, respectively, while the levels of FASN mRNA in cancer and non-cancer tissues were determined as 104.8±100.8 and 105.1±100.5 copies/μg total RNA, respectively." (PMID 24649254, 2013). "Although the molecular mechanisms of ACLY inhibition-dependent cell death are still not clear, these data suggest that this enzyme could also be a target for cancer therapy." (PMID 19352381, 2009). "Interestingly, ESRP1 expression is not correlated with poor survival in a pan-cancer analysis, in contrast to ACLY PSI, suggesting that additional factors may influence ACLY splicing and associated phenotype(s)." (PMID 38815867, 2024). "Since cancer cells are adept at engaging available metabolic flexibility mechanisms, we hypothesized that noncanonical acetyl-CoA production mechanisms could be revealed by developing ACLY KO cancer cell models that are not dependent on acetate for viability." (PMID 37134161, 2023). "In addition, interestingly, lipogenic genes, including SREBFs, ACLY and FASN, were reduced by LPIN1 knockdown, suggesting that LPIN1 is not a passive lipogenic gene but a driver gene that actively induces alterations in lipid metabolism in TKI-resistant cancer cells." (PMID 35565351, 2022). "During lactation, breast tissue shows significantly higher expression of ACLY and ACSS2 genes than in the dry milk stage, and this is mirrored in cancer cells as opposed to normal cells." (PMID 41300803, 2025). "Meanwhile, these genes regulated by SREBP-1, including ACLY, ACC, FASN, and SCD, are highly expressed in cancer tissues compared to adjacent non-tumor tissues, which play essential roles in the growth, metastasis, and survival of various cancers." (PMID 35912181, 2022). "ACLY transcription is promoted by SREBP1, but the significant decrease in ACLY mRNA expression in some of the cancer cells observed in the combined treatment may not completely be due to SREBP1." (PMID 37958642, 2023).
tumor (258 papers, 2006 to 2026). "In another instance, a micropeptide encoded by an lncRNA maintained acetylation of ACLY (ATP-citrate lyase), promoting lipid accumulation and tumour progression." (PMID 41394868, 2025). "High ACLY expression correlates with increased risk of lymph node and distant metastasis, poorer tumour differentiation, and advanced clinical stages." (PMID 41154605, 2025). "We also demonstrate that pharmacological blockade of SLC25A1 and ACLY increases cell susceptibility to ferroptosis and markedly enhances ferroptosis-induced tumor suppression." (PMID 39881208, 2025). "ACLY is the first crucial enzyme in the production of acetyl-CoA, and its overexpression is associated with pathological grading, tumor size, and lymph node metastasis." (PMID 39179991, 2024). "Recent studies revealed that ACLY knockdown in tumor cells can cause oxidative stress in tumor cell mitochondria, inhibit cell growth, and promote apoptosis through citrate accumulation." (PMID 34047477, 2021). "One possible reason is that the upregulated fatty acid synthesis caused by ACLY activity in tumor cells saturates membrane lipids, thereby leading to drug resistance and affecting therapy response." (PMID 31077215, 2019). "Mutations in exon 2 of MED12 were identified in 39% (14 of 36) of LM tumor specimens, and the ACLY gene was mutated in 6% (two of 36) of LM tumor specimens." (PMID 32232185, 2019). "Though, overall expression of both enzymes correlated positively, ACLY was associated with local tumor stage, whereas ME correlated with occurrence of mediastinal lymph node metastases." (PMID 25962060, 2015). "To further evaluate the modifying effect of host characteristics on association of SNPs in ACLY gene with the prognosis, we performed a stratified analysis in patients with early stage and advanced stage tumor." (PMID 25890184, 2015). "It’s known that tumor-associated macrophages (TAMs) create an inflammatory environment that facilitates survival and proliferation of tumor cells, but the role of ACLY-mediated metabolic rewiring of macrophages in tumorigenesis remains unclear." (PMID 34050894, 2022). "Several studies have associated ACLY expression in tumor tissues with worse prognosis." (PMID 33194695, 2020). "Interestingly, there was a significant increase of SLC2A1gene associated with hypoxia response and ACLY gene associated with metabolism in the tumor tissues compared to the healthy tissue." (PMID 25575813, 2015). "Arginine-activated mTOR is implicated in tumor cell growth and proliferation but also epigenetic reprogramming; mTOR promotes acetyl-CoA synthesis through the activation of ATP citrate synthase (ACLY) and Acyl-coA synthetase short-chain family member 1–2 (ACSS 1–2)." (PMID 37568713, 2023). "In vivo, AMPK-ROS axis activation through ACLY inhibition or resetting of drug responsiveness can be connected to tumor suppression and increased sensitivity." (PMID 42193163, 2026). "In conclusion, these studies have shown that genetic inhibition of ACLY in MASH-driven mouse models of HCC promotes the infiltration of tumour-infiltrating B cells and that this is critical for reducing tumour burden." (PMID 40739358, 2025). "High ACLY expression correlates with advanced tumour stages and lymph node metastasis, indicating its role in tumour aggressiveness." (PMID 41154605, 2025). "Together, these data in both mice and humans strongly suggest that inhibition of ACLY is the primary driver of the enhanced tumour immunogenicity, mediated by EVT0185." (PMID 40739358, 2025). "Oncogenic KRAS mutations synergize with ACLY and ACSS2 enzymatic activities to drive tumor cell proliferation and metastatic progression." (PMID 40814339, 2025). "ATP citrate lyase (ACLY), a rate‐limiting enzyme of de novo lipid synthesis, plays an important role in tumor progression and chemotherapy." (PMID 41038802, 2025).
tumor (continued). "Here, using a mouse model of MASH-HCC that mirrors human disease, genetic inhibition of ACLY in hepatocytes and tumours reduced neoplastic lesions by over 70%." (PMID 40739358, 2025). "Lactate accumulation increases ACLY activity through H3K18la modification, further driving lipid synthesis and tumor cell growth in PC." (PMID 41051446, 2025). "We observed that exogenously expressed ACLY reversed the anti-tumor effects induced by USP13 depletion." (PMID 41330897, 2025). "Other natural agents, such as berberine, similarly suppress ACLY activity, thereby attenuating tumor progression and metastatic potential." (PMID 40735327, 2025). "And inhibition of key enzymes of FA synthesis and β-oxidation (e.g., acetyl coenzyme A carboxylase, acetyl coenzyme A synthase, ATP citrate lyase, and carnitine palmitoyltransferase 1 C) inhibits tumor cell growth and delays disease progression." (PMID 40650680, 2025). "These epigenetic modifications activate the transcription of ATP citrate lyase (ACLY) through chromatin remodeling, ultimately promoting malignant tumor progression by enhancing lipid biosynthesis metabolism." (PMID 41051446, 2025). "Through these roles, ACLY supports both the anabolic growth demands of tumour cells and epigenetic regulation of gene expression." (PMID 40739358, 2025). "Genetic inhibition of ACLY increased tumour infiltration by B cells and upregulated the B cell chemoattractant CXCL13, promoting the formation of TLSs, immune niches associated with favourable prognosis in HCC and other solid tumours." (PMID 40739358, 2025). "Conversely, deubiquitinases USP13 and USP30 stabilize ACLY, promoting tumor progression in cancers such as ovarian and liver cancers." (PMID 40370434, 2025). "Overexpression of ACLY, a key gene in the flow of citric acid to lipid metabolism, was observed in epithelial cells derived from tumor samples." (PMID 39988626, 2025). "Curcumin, a natural compound, also inhibits ACLY activity, lowering acetyl-CoA levels and disrupting lipid synthesis essential for tumor growth." (PMID 40735327, 2025). "Research has demonstrated that overexpression of ACLY stimulates the proliferation of tumor cells, whereas suppression of ACLY expression hinders their growth." (PMID 39925801, 2025). "Although ACLY inhibition shows antiproliferative effects in various tumours, clinical translation has been limited by challenges in inhibitor development and compensatory metabolic pathways." (PMID 40739358, 2025). "ACLY is a key enzyme that directs excess glycolytic flux ATP to lipid synthesis to promote tumor growth and differentiation." (PMID 40814339, 2025). "Mechanistically, RBM15 regulates downstream target ATP citrate lyase (ACLY) expression via m6A modification, which is recognized by IGF2BP2, thereby activating ACLY, driving lipid biosynthesis, and enhancing tumor malignancy." (PMID 41403702, 2025). "Certain important enzymes involved in fatty acid synthesis, including ATP citrate lyase (ACLY), acetyl-CoA carboxylase (ACC), and fatty acid synthase (FASN), are upregulated in tumors and linked to aggressive tumor behavior and unfavorable prognosis." (PMID 40492126, 2025). "ACLY is also significantly upregulated in HCC tissues and associated with poor prognosis and advanced tumour stages." (PMID 41154605, 2025). "FASN and ACLY immunohistochemistry tumor staining of PDX samples validated what it was previously observed in vitro." (PMID 38425123, 2024). "Based on clinical evidence and functional analysis, we concluded that ACLY plays a potential role in CCA tumor progression." (PMID 39399493, 2024). "Together, these data reveal the expression of two ACLY splice isoforms in mouse and human tissues and indicate that ACLY is a component of the splicing program mediated by ESRP1, a factor that has been implicated in tumor progression." (PMID 38815867, 2024). "Increased levels of lipid-producing enzymes, including ACLY, are common in PDAC, and inhibiting ACLY suppresses tumor growth." (PMID 39682280, 2024).
tumor (continued). "In additionally, in our previous study, we found that inhibition of ACLY disrupts the balance between saturated and unsaturated fatty acids within tumor cells." (PMID 39399493, 2024). "Our investigation revealed that specifically reducing the activity of ACLY significantly suppressed the promotion of tumor growth and the enhancement of fatty acid production induced by overexpression of ZDHHC6." (PMID 39148124, 2024). "Previous studies have proved that the expressions of ACLY were increased in gastric cancer, ovarian cancer, prostate cancer, lung cancer, etc., and correlated with increased tumor aggressiveness and poor patient prognosis." (PMID 39399493, 2024). "In vitro studies have shown that inhibition of ACLY can limit tumour proliferation and induce apoptosis." (PMID 38426936, 2024). "Since FAs are limited in the human body for fast-growing tumors, many tumor cells synthesize unsaturated FAs by de novo synthesis pathway, modulated by several key enzymes such as ACLY, SCD, FASN, and ACC." (PMID 38560498, 2024). "ACLY is overexpressed in several tumor types, and inhibition or knockout (KO) impairs lipid synthesis and tumor growth in vivo." (PMID 38815867, 2024). "ACLY, as the first regulatory enzyme for de novo lipid synthesis, plays an essential role in reprogramming tumor lipid metabolism." (PMID 39584783, 2024). "Tumor cells engage in de novo synthesis of fatty acids, which is mainly contributed by ATP-citrate lyase (ACLY), acetyl-CoA carboxylase (ACC), and fatty acid synthase (also known as FASN)." (PMID 38216787, 2024). "Conversely, mammalian SIRT6 has ACLY‐dependent histone deacetylation activity and can promote the expression of tumor suppressor and aging‐related genes to suppress the aggressive cancer cell phenotypes." (PMID 39584783, 2024). "Many studies have shown that ACLY is highly expressed in various tumours, and its pharmacological or gene inhibition significantly inhibits tumour growth and progression." (PMID 38426936, 2024). "Based on these results, we propose that inhibiting ACLY can enhance ferroptosis in tumor cells, highlighting its potential as a therapeutic target." (PMID 39399493, 2024). "Fourth, IKKβ‐USP30 (ubiquitin‐specific peptidase 30)‐ACLY axis, which is a novel tumor cell regulatory axis, was recently identified to be upregulated in HCC." (PMID 39584783, 2024). "ACLY, as the “initiation” enzyme of de novo fatty acid synthesis, plays an extremely key role in tumour fat synthesis and participates in tumour progression and metastasis." (PMID 38426936, 2024). "Instead of being exported outside the cell, cytosolic tumour citrate is cleaved by ATP citrate lyase to form acetyl-CoA and fuel lipogenesis, to sustain membrane biosynthesis in the proliferating cells." (PMID 39013948, 2024). "As key rate-limiting enzyme in de novo fatty acid synthesis, silencing ACLY can inhibit the proliferation of multiple tumor cells lines, and exogenous supplementation with fatty acids or cholesterol can partially counteract the proliferation inhibition effect." (PMID 39399493, 2024). "Whereas, ACLY inhibition reduces tumorigenesis in vivo, implying the importance of fatty acid biosynthesis in tumor formation." (PMID 38402237, 2024). "Our findings also demonstrated that ACLY knockdown or pharmacological inhibition promotes ferroptosis in tumor cells, as evidenced by a significant increase in intracellular lipid peroxides and malondialdehyde (MDA) levels." (PMID 39399493, 2024). "In breast cancer, augmented levels of SMARCA4 enhance fatty acid synthesis through the transcriptional activation of lipogenic genes, such as ACC, FASN, and ACLY, facilitating rapid tumor growth through escalated DNL." (PMID 38374872, 2024). "The results showed that ACLY was highly expressed in 25 of 34 different tumour types, including ESCA." (PMID 38426936, 2024). "In this study, we observed that ACLY expression in CCA tissues was significantly elevated compared to adjacent non-tumor tissues." (PMID 39399493, 2024).